CYP11B1 (cytochrome P450 family 11 subfamily B member 1)
Diseases named in the same sentence as CYP11B1 in open-access papers (continued):
Sharing a sentence is not in itself a finding about the gene and the disease.
hyperuricemia (1 paper, 2023). An abnormally high level of uric acid. "Compared with the control mice, the mRNA levels of enzymes such as cytochrome P450 family 11 Subfamily a member 1 (CYP11A1), 11β-hydroxylase (CYP11B1), aldosterone synthase (CYP11B2) and 3β-hydroxysteroid dehydrogenase 1 (HSD3B1) were significantly lower in the adrenal of hyperuricemia mice." (PMID 38034015, 2023).
intestinal tumours (1 paper, 2023). "Most importantly, 11β‐hydroxylase appears to be essential for glucocorticoid synthesis in the intestinal epithelium and intestinal tumours, as Cyp11b1 deletion abrogated it." (PMID 36861295, 2023).
ischemic stroke (1 paper, 2022). A stroke disorder caused by obstruction of blood flow to the brain, due to thrombotic (local blood clot formation) or embolic (due to a blood clot or other material traveling from another site) event. "Correlation of CYP11B1 polymorphisms and ischemic stroke susceptibility stratified by age and gender." (PMID 36532271, 2022). "Correlation of CYP11B1 polymorphisms and ischemic stroke susceptibility stratified by smoking and drinking." (PMID 36532271, 2022). "Association between CYP11B1 gene polymorphisms and ischemic stroke susceptibility." (PMID 36532271, 2022).
liver cirrhosis (1 paper, 2022). "Similarly, little is known about the expression of CYP11B1 in liver cirrhosis, and we detect it to be upregulated by 77%." (PMID 35579278, 2022).
preeclampsia (1 paper, 2024). Preeclampsia is a hypertensive disorder of pregnancy that is characterized by new-onset hypertension with proteinuria presenting after 20 weeks of gestation, and depending on mild or severe forms may initially present with severe headache, visual disturbances, and hyperreflexia. "We identified CYP17A1, HSD17B3, SRD5A1, CYP19A1, CYP11B1, HSD11B1 and HSD11B2 as potentially affected enzymes in preeclampsia." (PMID 39684415, 2024). "mRNA expressions of genes of enzymes with significantly decreased precursor-to-product ratios (i.e., CYP17A1, HSD17B3, CYP11B1 and HSD11B2) was similar in women with preeclampsia and controls, but the RNA levels of these genes were higher in women with preeclampsia." (PMID 39684415, 2024).
prostate carcinoma (1 paper, 2023). A carcinoma that arises from epithelial cells of the prostate gland. "Exome sequencing analyses of a subset of AA and EA men revealed that AA men with prostate cancer had a significantly higher frequency of multiple SNPs in the genes encoding CYP11B1 and CYP11B2." (PMID 36837903, 2023).
tumor (29 papers, 2013 to 2025). "We next transplanted Cyp11b1‐proficient and Cyp11b1‐deficient tumoroids into lymphopenic Rag1‐deficient mice to monitor the contribution of T and B cells in the control of tumour growth." (PMID 36861295, 2023). "Clearly, Cyp11b1‐deficient tumours still grew slower, even in T‐cell‐depleted Rag‐deficient mice, and had increased numbers of infiltrating macrophages, dendritic cells, neutrophils and NK cells." (PMID 36861295, 2023). "While IL‐10 expression was not significantly different, there was a tendency towards lower expression in Cyp11b1‐deficient tumours (P = 0.0837)." (PMID 36861295, 2023). "Aldosterone synthase (CYP11B2)/cortisol synthase (CYP11B1) immunostaining profiles represent a hallmark of the modern approach regarding unilateral tumours with aldosterone and/or cortisol excess." (PMID 36428832, 2022). "The CYP11B1 IHC staining of cNGS-identified mutation carriers demonstrated that the density of CYP11B1 staining was similar between tumor and adjacent tumoral regions." (PMID 34572353, 2021). "Cyp11b1‐deficient mice not only showed reduced tumour numbers, but tumours were also smaller." (PMID 36861295, 2023). "Furthermore, Cyp11b1‐deficient tumours had reduced expression of the immunoregulatory molecules CD274 (PD‐L1), CD152 (CTLA‐4) and IL‐10." (PMID 36861295, 2023). "These analyses of immune cell infiltrates in Cyp11b1‐proficient and Cyp11b1‐deficient transplanted tumours revealed substantial changes in innate immune cell populations, especially dendritic cells, macrophages, natural killer (NK) cells and neutrophils at day 9 post transplantation." (PMID 36861295, 2023). "Another study showed a correlation between increased A/CPA tumor volume and increased CYP11B1 expression, along with decreased CYP11B2 expression." (PMID 39010034, 2024). "In the inflammation phase, LRH‐1/Nr5A2‐regulated and Cyp11b1‐mediated intestinal glucocorticoid synthesis prevents tumour development and growth." (PMID 36861295, 2023). "Our data, in contrast, indicate that CYP11B1 expression and activity in tumor cells and tumor-infiltrating cells is minimal and that 11β-HSD1 is the primary source of intratumor glucocorticoid production." (PMID 37471141, 2023). "In established tumours, however, tumour‐autonomous Cyp11b1‐mediated glucocorticoid synthesis suppresses anti‐tumour immune responses and promotes immune escape." (PMID 36861295, 2023). "Immunohistochemical staining for SF-1, P450scc, CYP17A, CYP21A, and CYP11B1 indicated that this tumor produced cortisol." (PMID 35966069, 2022). "Individuals with positive immunostaining for CYP11B1 correlated with wild-type KCNJ5 (p = 0.018), respective CYP11B2 positive was more often found in tumours with KCNJ5 mutation (p = 0.007)." (PMID 36428832, 2022). "Both CYP21A2 and CYP11B1 had discrepant dominant transcripts between the tumours, mirrored by a great range of total expression of these genes in the cohort, with some samples having very high expression and others very low." (PMID 31000732, 2019). "IHC staining and western blot analyses revealed that both the A/CPA and pure APA tumor tissues were positive for CYP11B1, CYP11B2, and CYP17A1, implying that these tumors can produce both aldosterone and cortisol." (PMID 29770148, 2018). "Similarly, when Cyp11b1 was deleted in vitro by transducing Cyp11b1L/L tumour organoids with lentiviral Cre recombinase, a similar growth advantage of Cyp11b1‐proficient tumours over Cyp11b1‐deleted tumours was observed upon s.c. transplantation." (PMID 36861295, 2023). "However, during the tumor phase, glucocorticoid synthesis mediated by Cyp11b1 suppresses anti-tumor immune responses, promoting immune evasion." (PMID 38012609, 2023). "Therefore, tumors were implanted in CYP11B1-deficient (Cyp11b1Actin–Cre) mice, which have low levels of circulating glucocorticoids and thus reduced amounts of DHC for tumor cell 11β-HSD1 to recycle." (PMID 37471141, 2023).
tumor (continued). "Metabolic activation of mitotane may be dependent on CYP11B1, or others CYPs, and the ability of the tumor to metabolize mitotane may predict the response to treatment." (PMID 36558937, 2022). "The results showed that CYP11B1 (encoding 11β-hydroxylase), CYP11B2 (encoding aldosterone synthase), and Ca metabolism-related receptors (CaSR, VD3R, and PTH1R) were positively expressed in the same region of tumor tissue." (PMID 35960046, 2022). "In situ metabolomics is correlated with a CYP11B1/B2 stain and tumour genotype." (PMID 36428832, 2022). "Indeed, we observed concurrent elevations of 11OHA4, 11OHT, cortisol and corticosterone (a CYP11B1/2 product) in cases supporting the hypothesis of a systemic adrenal response to tumor-related stress or immune activation." (PMID 40427176, 2025). "Notably, while in untreated recipient mice, Cyp11b1‐proficient tumours grew faster and bigger than Cyp11b1‐deficient ones, no statistical difference was observed anymore in dexamethasone‐treated recipient mice." (PMID 36861295, 2023). "However, with the increase in tumor volume, the CYP11B1 expression level was further increased." (PMID 35960046, 2022). "In the fifteen tumours subjected to RNA-Sequencing in this study, opposite patterns of expression in tumours with mutations in KCNJ5 and those with mutations in CACNA1D/ATP1A1/ATP2B3 were observed, with KCNJ5-mutants showing higher levels of CYP11B1 expression and lower levels of CYP11B2 expression." (PMID 31000732, 2019). "In addition, the tumor displayed positivity for steroidogenic enzymes CYP11B1 and CYP21A2." (PMID 24616772, 2013). "Immunohistochemical analysis showed that the tumor cells were positive for P450scc, P450c17, P450c21, and CYP11B1; faintly positive for DHEA sulfotransferase (DHEA-ST); and negative for CYP11B2; confirming the cortisol-producing ability of the tumor." (PMID 39430734, 2024). "Importantly, differences in genetic mutations of the transplanted tumours could be excluded as in vitro deletion of the Cyp11b1 gene in tumour organoids by lentiviral Cre transduction resulted in similar reduced tumour growth upon s.c. transplantation." (PMID 36861295, 2023). "However, it remained possible that TAM Cyp11b1 could be a driver of tumor growth." (PMID 37471141, 2023). "We are unaware of such comparisons of tumor cells prior to our study, but in normal mouse skin corticosterone production by 11β-HSD1 dwarfed that of Cyp11b1, as we observed." (PMID 37909339, 2023). "The tumor cells were partially positive for CYP11B1 and negative for CYP11B2, which was consistent with the findings of CPA." (PMID 40568364, 2025). "The tumor cells were positive for CYP11B1 and negative for CYP11B2, consistent with the findings of a CPA." (PMID 40568364, 2025). "In one particular study, CYP11B1 was found to be expressed exclusively in tumor tissue from a patient with PA but without significant CS." (PMID 39010034, 2024). "However, for the seven glucocorticoid-producing tumor cells we examined, the amounts regenerated by 11β-HSD1 were vastly greater than those synthesized by Cyp11b1, and inhibiting 11β-HSD1 substantially enhanced antitumor immunity and reduced tumor growth." (PMID 37909339, 2023). "The data thus far support the notion that 11β-HSD1–mediated regeneration, not Cyp11b1-mediated synthesis, is the major source of biologically, and perhaps clinically, relevant tumor-derived glucocorticoids." (PMID 37909339, 2023). "Our results show that tumours lacking LRH‐1 expression or its transcriptional target Cyp11b1 fail to produce tumour‐autonomous glucocorticoids, which results in better control of the tumour growth by tumour‐infiltrating immune cells." (PMID 36861295, 2023). "Further immunostaining with adrenocortical enzymes revealed that all these tumor components were CYP11B1 positive and CYP11B2 negative, indicating cortisol-producing tumors." (PMID 35660748, 2022).
tumor (continued). "The CYP11B1 immunoscore adjusted for tumor area was not correlated with serum potassium (r = −0.079, p = 0.398)." (PMID 34631800, 2021). "(iii) APCCs express CYP11B2, but not CYP11B1, whereas APAs consist of heterogeneous tumor cells expressing either CYP11B2 or CYP11B1." (PMID 27721827, 2016). "Tumor-infiltrating cells do not express functionally significant levels of Cyp11b1." (PMID 37471141, 2023). "Of interest, while we have seen significant differences in overall patient survival between tumours with high versus low CYP11A1 expression, we have not been able to conduct the same analysis for CYP11B1, as expression was not reported for all tumour tissues summarized in the TCGA database." (PMID 36861295, 2023). "Bilateralism of the tumours, presence of Reinke crystals and expressions of synaptophysin, Inhibin α, CD56, androgen receptor, DLK1, INSL3, CYP11B1, CYP21A2 and MC2R have all been studied as potential markers, but none of these markers individually can reliably discriminate TARTs from LCTs." (PMID 29038332, 2017). "The metabolic activation of mitotane may take place in the tumor and be dependent on either CYP11B1 or a non-steroidogenic CYP, and there is some evidence that the capability of the tumor to metabolize mitotane may predict response to treatment." (PMID 29734384, 2018).
cancer (7 papers, 2020 to 2024). A tumor composed of atypical neoplastic, often pleomorphic cells that invade other tissues. "Altogether, HSD3B1, HSD3B2, CYP11A1, CYP11B1, CYP17A1, and CYP3A43, hereby defined as APUC-6, demonstrated tissue- and cancer stage–specific interactions, with the most notable interaction in metastatic PC." (PMID 39207857, 2024). "In humans, HSD11B1 was expressed in many cancer types, but CYP11B1 and CYP11B2 had low or absent expression." (PMID 37909339, 2023).
cardiovascular disease (2 papers, 2022 to 2023). "Human aldosterone synthase (CYP11B2) and cortisol synthase (CYP11B1) have been exploited in inhibitor screening campaigns to identify treatments for cardiovascular disorders and cortisol-related diseases, which affect specific cellular responses to compounds for drug development." (PMID 38036976, 2023).
benign tumors (1 paper, 2020). "When comparing the two subgroups of benign tumors, CYP11B1 and StAR were the steroidogenic proteins that were most differentially expressed in ACAn and ACAc, with lower levels of both proteins found in non-functioning ACA." (PMID 32751564, 2020).
infection (1 paper, 2015). The state of being infected such as from the introduction of a foreign agent such as serum, vaccine, antigenic substance or organism. "The cyp19a1a expression was up-regulated at 1 day post infection, whilst the cyp11b1 expression was unchanged." (PMID 26691348, 2015). "Thus, the expression of cyp11b1 was up-regulated at day 7 and erb1 and erb2 genes at day 1 and 7, respectively, while the three genes were down-regulated at day 15 of infection." (PMID 26691348, 2015).
psychiatric disorder (1 paper, 2019). A disorder characterized by behavioral and/or psychological abnormalities, often accompanied by physical symptoms. "We then examined methylation in a shortlist of genes that were previously associated with early life stress and psychiatric disorders as well as placental functioning: Ank3, Avp, Avpr1a, Avpr1b, Bdnf, Cacna1c, Cyp11b1, Cyp11b2, Fkbp5, Hsd11b1, Igf2, Morc1, Nr3c1, Oxt, Oxtr, Pclo, Slc6a4." (PMID 30655507, 2019).
CYP11B1 also shares sentences with these, for which no sentence is quoted: primary aldosteronism (6 papers); 11-beta-hydroxylase deficiency (4); achromatopsia (1); adrenal cancer (1); androgen excess (1); breast carcinoma (1); cervical cancer (1); colon carcinoma (1); coronary heart disease (1); diabetes (1); endometriosis (1); essential hypertension (1); familial hyperaldosteronism type II (1); Friedreich ataxia (1); gastrointestinal stromal tumor (1); gastrointestinal tumors (1); Gaucher disease (1); Gordon syndrome (1); Hirsutism (1); inflammatory bowel disease (1); leukemia (1); Liddle syndrome (1); lymphoma (1); Malignant Adrenocortical Tumors (1); metabolic disease (1); metachromatic leukodystrophy (1); mineralocorticoid excess (1); neurological abnormalities (1); Niemann-Pick disease (1); ovarian carcinoma (1).
A further 11 diseases each share a sentence with CYP11B1 in 1 paper.